IGKV1D-42 (immunoglobulin kappa variable 1D-42 (non-functional))
Description:
Probable non-functional open reading frame (ORF) of V region of the variable domain of immunoglobulin light chains. Non-functional ORF generally cannot participate in the synthesis of a productive immunoglobulin chain due to altered V- (D)-J or switch recombination and/or splicing site (at mRNA level) and/or conserved amino acid change (protein level). Immunoglobulins, also known as antibodies, are membrane-bound or secreted glycoproteins produced by B lymphocytes. In the recognition phase of humoral immunity, the membrane-bound immunoglobulins serve as receptors which, upon binding of a specific antigen, trigger the clonal expansion and differentiation of B lymphocytes into immunoglobulins-secreting plasma cells. Secreted immunoglobulins mediate the effector phase of humoral immunity, which results in the elimination of bound antigens. The antigen binding site is formed by the variable domain of one heavy chain, together with that of its associated light chain. Thus, each immunoglobulin has two antigen binding sites with remarkable affinity for a particular antigen. The variable domains are assembled by a process called V-(D)-J rearrangement and can then be subjected to somatic hypermutations which, after exposure to antigen and selection, allow affinity maturation for a particular antigen.
Synonyms: IGKV1D42; L22
Gene: Immunoglobulin variable (V) gene on chromosome 2 (90,190,193 to 90,190,681, forward strand). Ensembl gene ENSG00000211633.
Subcellular location: Secreted; Cell membrane
Gene Ontology:
Biological process: immune response
Cellular component: extracellular region; immunoglobulin complex; plasma membrane
Homologues: Orthologues: mouse Igkv15-103 (64% identical), macaque IGKV1D-42 (59% identical). Paralogues in human: IGKV1-9 (78% identical), IGKV1D-13 (78% identical), IGKV1-12 (76% identical), IGKV1-39 (75% identical), IGKV1D-12 (75% identical), IGKV1D-39 (75% identical), IGKV1-5 (74% identical), IGKV1-6 (74% identical), IGKV1D-16 (74% identical), IGKV1-17 (74% identical), IGKV1D-43 (74% identical), IGKV1-16 (73% identical), and 81 more.